SMG1P5 (SMG1 pseudogene 5)
Gene: Transcribed unprocessed pseudogene on chromosome 16 (30,267,553 to 30,335,054, reverse strand). Ensembl gene ENSG00000183604.
Diseases named in the same sentence as SMG1P5 in open-access papers:
SMG1P5 is named in the same sentence as 1 disease in open-access papers, as found by Europe PMC text mining. Sharing a sentence is not in itself a finding about the gene and the disease. The quoted sentences say what the papers report.
cancer (1 paper, 2017). A tumor composed of atypical neoplastic, often pleomorphic cells that invade other tissues. "We detected insertion at the intronic region of RBM4 (chr11), known to be associated with cancer and ncRNA SMG1P5 (chr16), downstream of TINAGL1 (chr1) and LOC339807 (chr2) and at an intergenic region that is 30Kb upstream of ZNF846 and 11Kb downstream of FBXL12 in chromosome 19." (PMID 28410234, 2017).